KRTAP21-2 (keratin associated protein 21-2)
Description:
In the hair cortex, hair keratin intermediate filaments are embedded in an interfilamentous matrix, consisting of hair keratin-associated proteins (KRTAP), which are essential for the formation of a rigid and resistant hair shaft through their extensive disulfide bond cross-linking with abundant cysteine residues of hair keratins. The matrix proteins include the high-sulfur and high-glycine-tyrosine keratins.
Synonyms: KAP21.2
Tractability: No criterion of Open Targets' tractability assessment is met for any kind of drug.
Gene: Protein-coding gene on chromosome 21 (30,746,794 to 30,747,259, reverse strand). Ensembl gene ENSG00000187026.
Pathways (Reactome):
Developmental Biology: Keratinization
Gene Ontology:
Molecular function: protein binding
Cellular component: cytosol
Genetic constraint (gnomAD): Loss-of-function variants: 1 observed, 1.36 expected, observed/expected ratio (o/e) 0.73, 90% interval 0.22 to 1.85. That is too few expected variants to judge how well the gene tolerates losing a copy. Missense variants: 103 observed, 107.54 expected, observed/expected ratio (o/e) 0.96, 90% interval 0.82 to 1.13. Synonymous variants: 38 observed, 40.34 expected, observed/expected ratio (o/e) 0.94, 90% interval 0.73 to 1.24.